TNF (tumor necrosis factor)
Diseases named in the same sentence as TNF in open-access papers (continued):
Sharing a sentence is not in itself a finding about the gene and the disease.
infection (continued). "TNF-α blockade in experimental models of DENV infection resulted in prevention of disease and TNF-α action has been implicated in increased vascular permeability after infection in experimental settings." (PMID 22206036, 2011). "In contrast, TGF-β has also been shown to promote inflammation by inducing chemotaxis in human peripheral blood monocytes, enhancing their ability for transendothelial migration to sites of infection, and up-regulating the transcription of pro-inflammatory cytokines such as IL-1β and TNF-α." (PMID 21884610, 2011). "Also, we show that induction of mRNAs related to the IL-12/Th1 and TNF-alpha (TNFα) pathways occurs between D15–D21 post infection and coincides with cellular accumulation of Th1 cells and activation of myeloid cells in M.tuberculosis-infected lungs." (PMID 21249199, 2011). "TNF-α is an acute phase cytokine, which is released immediately following an infection." (PMID 21249123, 2011). "TNF-α induction has a serious impact on T. gondii induced pathology at early stages of infection." (PMID 21957440, 2011). "Moreover, we indicated nDens of 2 genes induced and 2 genes repressed in all infection performed and nDens of all genes discussed above (IL-1β, IL-6, IL-12, TNF-α, IL-10, ADAM19, CCR7, CCL20 and IL-18)." (PMID 21436989, 2011). "Moreover, this infection induces an enhanced expression of soluble pro-inflammatory factors, including TNF-α and the active gMMP-9, as well as a decreased expression of anti-inflammatory cytokines, such as IL-10 and TGF-β." (PMID 21569520, 2011). "In five anti-dsDNA-NcX false-positive disease controls, we found other circumstances potentially causing elevated autoantibody levels, such as minocycline, sulfasalazine, TNF inhibitors and an unknown infection with fever." (PMID 21329504, 2011). "Additionally, inflammatory Gr1+/Ly6Chigh monocytes are able to differentiate into tumor necrosis factor-α (TNF-α) and inducible nitric oxide synthase (iNOS) producing so-called Tip-DCs at sites of infection." (PMID 21494554, 2011). "However, control of inflammation was not sustained as a significant increase (p<0.01) in lung weights was evident in Tm-TNF mice at day 322 post-infection compared to WT mice." (PMID 22132068, 2011). "Our data demonstrates that the down regulation of SOD1 is likely to be due to post transcriptional processes and may be related to up regulation of TNFα following infection." (PMID 21655261, 2011). "Hence, we tested if Sn infection can prevent cytochrome c release from the cells treated with TNF/Chx induction." (PMID 21799887, 2011). "We propose that increased IL-1 and equivalent TNF-α mRNA expression in the skin of ImmuPatch vaccinated mice could be due to MVA infection of keratinocytes that constitute the majority of the epidermis and are major producers of these cytokines." (PMID 21799855, 2011). "The fibroblasts expressed significant levels of TNFα 24 h post infection." (PMID 22206025, 2011). "Interestingly, from the day 4 post-infection SMI-049-infected macrophages produced much greater amounts of TNF than macrophages infected with H37Rv." (PMID 21304944, 2011). "Having shown that T. brucei driven transitional B-cell apoptosis occurs in a TNF-, Fas- and prostaglandin-independent manner, our study next focused on a model system that could help to functionally unravel infection-induced B-cell apoptosis." (PMID 21738467, 2011). "It was proposed that early TNF-α production during WNV mouse infection could be a potential factor responsible for an increase in the permeability of the BBB." (PMID 21949747, 2011). "Interestingly, higher levels of TNF-α were observed during either PbWt or PbAOX-aRNA conidia-alveolar macrophages interaction when compared to yeast cells after 30 min of infection of IFN-g-activated alveolar macrophages." (PMID 22039556, 2011). "Reactivation and new infection are both possible in patients with RA treated with anti-TNF therapy." (PMID 21605439, 2011).
infection (continued). "To test whether Simkania confers apoptosis resistance during infection, we induced apoptosis with tumor necrosis factor alpha (TNF-α) in the presence of cycloheximide (TNF/Chx) in infected and non-infected HeLa cells." (PMID 21799887, 2011). "Seven days post infection, the probiotic administration (Lc-S and Lc-S-Lc grups) was able to maintain TNFα production in the lamina propria of the small intestine and its secretion to the intestinal fluid similar to the observed in the non infected groups (C and Lc groups)." (PMID 21813005, 2011). "Finally, the TNF-α released and accumulated in the supernatant for 24 h after infection resulted high and similar in all the infections, as compared to uninfected DCs (P < .001)." (PMID 21436989, 2011). "Excessive systemic TNF is responsible for many symptoms of clinical infection and may lead to fatal complications." (PMID 22172537, 2011). "The inability of Tm-TNF mice to control development of further pathology was clearly evident at day 322 post-infection where, in contrast to WT mice, Tm-TNF mice displayed enlarged unstructured lesions with excess inflammatory responses and interstitial pneumonia." (PMID 22132068, 2011). "It is possible that the iNOS+ DC subset identified in vivo represents the inflammatory TipDC (TNFα+iNOS+CCR2+) which are recruited into the splenic T zone early during infection with Listeria monocytogenes or other pathogens as they were also CD11cint in our analysis (unpublished observation)." (PMID 22110693, 2011). "We found whole lipid extracts from the clinical strains induced a similar pattern of TNF-α expression from macrophages to the live infections, strongly suggesting these molecules influence the innate immune response to infection with different M. tuberculosis strains." (PMID 21931620, 2011). "Interestingly, CTC administration only decreased expression of IL-17A mRNA at the late stage of infection in the current study, perhaps due to the concomitant down-regulation of TNF-α and IL-1β mRNA expression." (PMID 21943280, 2011). "Upon infection, CD11b+ DCs primarily secrete low levels of TNFα while CD8α+ DCs secrete IL-12 p70." (PMID 21559416, 2011). "Results showed that MDDCs with AG genotype had significantly higher TNFα production than those with AA genotype at 24 and 48 hr post-infection (303.51±66.75 pg/mL vs. 143.97±68.80 pg/mL and 202.35±19.35 pg/mL vs. 73.00±9.55 pg/mL; p = 0.021 and 0.002, respectively)." (PMID 21245921, 2011). "Both IFN-γ and TNF-α increased during the course of infection in adult lungs." (PMID 22185352, 2011). "TNF deficient mice exhibited mucosal hyperplasia even in the absence of infection and exuberant growth of the mucosa during OM, including the formation of mucosal polyps." (PMID 21269505, 2011). "In the quarters with persistent infection, TNF-α concentrations peaked later and remained elevated for longer than in the quarters with a transient infection, the mean maximal concentrations being 13.9 ng/mL (SE 4.9) at 30 h PC and 13.21 ng/mL (SE 8.1) at 12 h PC, respectively." (PMID 21414189, 2011). "TNF-α plays a critical role in host defenses against infection." (PMID 21816039, 2011). "It is prudent to discontinue anti-TNF agents at time of infection." (PMID 21605439, 2011). "These cytokines were also studied 7 days post infection and it was observed that mice from infection control group (S) and the group fed continuously with the probiotic strain maintained increased expression of both TNFα and IFNγ in the cells isolated from Peyer's patches." (PMID 21813005, 2011). "Tm-TNF mice displayed similar iNOS expression to WT mice at day 133 days post-infection." (PMID 22132068, 2011). "ΔSPI1 mutants of both serovars invaded approx. 5 times less efficiently than the wild-type strains and despite this, macrophages responded to the infection with ΔSPI1 mutants by increased expression of proinflammatory cytokines IL-1β, IL-8, TNFα, IL-23α and GM-CSF." (PMID 21314975, 2011).
infection (continued). "Based on the studies developed with the T. cruzi model, it has been shown that the inflammatory syndrome mediated by TNF-α during the acute phase of infection induces the activation of hypothalamus-pituitary-adrenal (HPA) axis with the consequent release of corticosterone." (PMID 21858238, 2011). "TNF-α is mainly produced by monocytes and macrophages after infection." (PMID 22032685, 2011). "In this model, belated type I IFN responses would result in delayed adaptive immune responses and decreased antiviral innate responses; the later deluge of pro-inflammatory cytokines, such as TNF-alpha, would contribute to organ damage and vascular leakage in lethal infection." (PMID 21994766, 2011). "Interestingly, and contrary to our expectations, the TNF-α secretion in Sphk-1++ infected macrophages was significantly reduced in comparison to WT infected macrophages during later time points of infection." (PMID 20498849, 2010). "However, 30% of the mice treated with both the IL-1β and the TNF-α depleting antibodies succumbed to CO92ΔyopH infection." (PMID 20565713, 2010). "However, during the chronic period of infection, TNF-α levels were approximately 2-fold higher in the naïve mice possibly reflecting an attempt by the host to limit proliferation of Mtb." (PMID 21048936, 2010). "Analysis of TNFα and IL-6 demonstrated Esx-1-dependent secretion, implying that Esx-1 promotes NFκB activation in macrophages in vitro, which could account for the increased TNFα seen in infections by wild type M. marinum in vivo." (PMID 20463815, 2010). "Furthermore, the infection with the nuoG mutant led to an increase in TNF-α secretion in human and murine macrophages." (PMID 20421951, 2010). "Seen especially in infants born before the completion of 34 weeks of gestation, amniotic fluid (AF) infection is often coupled with a proinflammatory response noted by the presence of cytokines such as tumor necrosis factor-alpha (TNF-α) and interleukin-6 (IL-6)." (PMID 20706662, 2010). "The induction of these cytokines/chemokines might be initially achieved by a trace amount of TNF-α secretion as detected during the initial phase of infection." (PMID 21108843, 2010). "We cannot exclude that differences in TNF-α or TGF-β production could be responsible for different rates of infection observed between OE and KO strains." (PMID 20585663, 2010). "TJA infection is a rare but severe complication in patients receiving TNFα blockers." (PMID 20637100, 2010). "How the nuoG mutant infection leads to an increase in TNF-α secretion by macrophages needs to be investigated in more detail but activation of transcription factors such as ATF-2, Elk-1 and c-Jun upon JNK activation have been reported and would lead to an increase in TNF-α gene transcription." (PMID 20421951, 2010). "However, the TNF-induced survival signaling pathway is required for retaining T cells at the developing granuloma site where they produce IFN-γ, activating macrophages in synergy with TNF to kill intracellular infections." (PMID 20463877, 2010). "At early stages of infection, these isolates induced significantly lower TNF-α production than the other isolates, and maintained this level until the end of infection, thus indicating failure to correctly induce the cytokine-dependent Th1-type protective immune response." (PMID 20500810, 2010). "TNF-α was induced by all subtypes beginning at the early phase of infection." (PMID 21108843, 2010). "Taken together Tip-DCs might resemble a double edged sword in the course of an infection with L. monocytogenes in that they provide the benefits of iNOS and TNF as well the adverse effects of type I IFN expression." (PMID 21179567, 2010). "IFN-γ and TNF-α cytokines are believed to be the key inducers of macrophage activation, and nitric oxide (NO) production and oxidative burst are required for parasite clearance in early stages of infection." (PMID 20706586, 2010).
infection (continued). "TLR activation upregulates transcription of proinflammatory cytokines interleukin-1β (IL-1β), tumor necrosis factor alpha (TNFα), and interleukin-6 (IL-6), which are essential for the recruitment of immune cells to the site of infection and controlling Mtb infection." (PMID 20808838, 2010). "However, when given 24 hours after an enhanced DENV infection, E60-N297Q completely protected against mortality; likewise, tissue viral load and systemic TNF-α levels in these mice at 3.5 days post-infection were significantly reduced." (PMID 20168989, 2010). "Similarly, studies have shown that MAP kinase signaling leads to reduced TNFα expression during infection." (PMID 20824205, 2010). "Infection relapse occurred in one case where the TNFα blocker was reintroduced at 3 months." (PMID 20637100, 2010). "As a specific example, the model predicts that if TNF is an early part of the wasting cascade, anti-TNF therapy may slow the progression of cachexia and subsequently suppress both infection and cancer spread." (PMID 20181145, 2010). "The factors elevated included A-SAA, a protein primarily synthesized by cells in the liver, high-level production of which is known to be induced during the acute phase response to infection, trauma or stress by pro-inflammatory cytokines including TNF-alpha, IL-6 and IL-22." (PMID 20463814, 2010). "While IL-18 expression did not change at any time point (data not shown), a robust up-regulation was detected in the expressions of IL-1β, -6, -8, and TNF-α at days 2 and 3 after infection with both MOI-1 and -5 of WNV, which coincided with increase in cell toxicity following WNV infection." (PMID 21034511, 2010). "Upon challenge infection, TcVac2-vaccinated mice expanded the IgG2b/IgG1 antibodies and elicited a substantial CD8+ T cell response associated with type 1 cytokines (IFN-γ and TNF-α) that resulted in control of acute parasite burden." (PMID 20706586, 2010). "Serum MIF peaked 9 h post-infection and then declined; IL-6 and TNF-α continuously increased." (PMID 20939898, 2010). "We evaluated whether TNF-α production is impaired during infection with NO-resistant (LTCP 393 and LTCP 15404) compared to NO-susceptible (LTCP 15171 and LTCP 15344) L. (V.)braziliensis isolates from antimony-refractory or antimony-responsive patients." (PMID 20633260, 2010). "Levels of TNF-α were significantly enhanced after infection of WT mice." (PMID 21206747, 2010). "Recently, we derived a mouse-adapted DV2 strain, D2S10, that produces a TNF-α-dependent fatal vascular permeability syndrome in interferon-α/β and γ-receptor-deficient (AG129) mice 4–5 days after intravenous (iv) infection with 107 plaque forming units (pfu) of virus." (PMID 20168989, 2010). "The study also observed no induction of TNF-α and IL-1β after 36 h of infection, but the antimicrobial response gene encoding cytochrome b-245 (CYBB) was up-regulated." (PMID 20854687, 2010). "TNF-α levels in these isolates continued to decrease throughout the infection." (PMID 20500810, 2010). "Here, we report that, intranasal infection of mice with CO92 delta yopH mutant results in an early pro-inflammatory response in the lungs characterized by an increase in the pro-inflammatory cytokines Tumor Necrosis Factor-alpha and Interleukin one-beta 24 hours post-infection." (PMID 20565713, 2010). "In RA patients exposed or not to TNFα blockers, previous surgical site infection is an identified risk factor of postoperative infection after orthopedic surgery and after TJA." (PMID 20637100, 2010). "Little is known about viral, especially latent, infections in anti-TNF-α treatments." (PMID 20633267, 2010). "Upon infection with Ye, IL-12 as well as TNF production was induced in CD4+ and CD4−CD8α−, but decreased in CD8α+ DCs, which in turn may account for reduced T-cell priming by CD8α+ DCs." (PMID 21124820, 2010). "A rapid oscillation of TNFα and IL1β in vivo occurs in response to infection." (PMID 20819226, 2010).
infection (continued). "Because CD4pos T cells are an important component of the anti-CMV immunity, our observations suggest that CMV infections are well controlled during anti-TNF treatments and bring new insight into the current knowledge of the risks of infection in patients treated with anti-TNF-α biotherapies." (PMID 20633267, 2010). "In contrast, stimulation of mDC taken at 12 weeks post infection resulted in 20 to 30% of cells producing TNF-α and a smaller but significant percentage producing IL-12, representing a 4- to 5-fold increase above preinfection levels regardless of disease outcome." (PMID 21203477, 2010). "Consistently, BALB/c BMDM responded by secreting large amounts of TNF upon infection with non-pathogenic but not facultative-pathogenic mycobacteria." (PMID 20831789, 2010). "Thus, the increase of intracellular ROS induced by infection of cells with the nuoG mutant is required for the increase in TNF-α secretion by infected cells." (PMID 20421951, 2010). "Thus both the differences in TNF-α production and the differences in T cell specificity induced by the two pathogens suggested a different outcome of infection which was assessed 17 weeks post-infection by post-mortem examination (see next section)." (PMID 20049086, 2010). "Interestingly, lymph node mDC taken prior to infection responded relatively poorly to short-term stimulation with a small proportion of cells producing TNF-α and IL-12." (PMID 21203477, 2010). "This study suggests that the outcome of TJA infections is particularly severe in rheumatic patients exposed to TNFα blockers, leading to hospitalization in an ICU in 20% of the cases, to death in 10% and to moderate to severe functional disability in about 40%." (PMID 20637100, 2010). "As predicted, the control mice and the TNF-α-/- mice rapidly succumbed to infection with CO92." (PMID 20565713, 2010). "For instance, depleting immunocompetent mice of TNFα, IFNγ, or neutrophils renders them much more susceptible to infection with LVS, but not to virulent subsp." (PMID 20967278, 2010). "The TNF-α production dynamics along the infection differed among the isolates analyzed." (PMID 20500810, 2010). "TNFα blockers were always withdrawn at the time of TJA infection." (PMID 20637100, 2010). "Some studies have also shown that this risk varies according to treatment of RA patients, with a higher risk of infections with anti-TNF (tumor necrosis factor) agents compared with non-biologic disease-modifying antirheumatic drug (DMARDs)." (PMID 20398273, 2010). "Altogether, these data suggest that YopH is involved in delaying or inhibiting the expression of TNF-α and IL-1β during plague pneumonia and may be involved in the overall delayed inflammatory response to this infection." (PMID 20565713, 2010). "We previously showed that TNF-α participates in the control of infection." (PMID 20633267, 2010). "Interestingly, rm-APC did reduce lung TNF-α and IL-12 levels 96 hours after infection; similarly, APC has been found to inhibit the LPS-induced production of TNF-α in vitro and in vivo." (PMID 20398279, 2010). "Further, because cellular organization undergoes dynamic changes with granuloma development and at different stages of immune response (innate versus adaptive) to TB infection, it can be a factor controlling the diverse activities of TNF according to the stage of infection in the lung tissue." (PMID 20463877, 2010). "DHS mediated inhibition of TNF-α secretion in infected WT macrophages rendered an anti-inflammatory environment and provided the second major reason for the sensitization of Sphk-1 inhibited macrophages to infection." (PMID 20498849, 2010). "In addition to infection, IRs are common in patients treated with anti-TNF-α therapies and are a frequent reason for discontinuation." (PMID 20569501, 2010).